MZT1 (mitotic spindle organizing protein 1)
Description:
Required for the recruitment and the assembly of the gamma-tubulin ring complex (gTuRC) at the centrosome. The gTuRC regulates the minus-end nucleation of alpha-beta tubulin heterodimers that grow into microtubule protafilaments, a critical step in centrosome duplication and spindle formation.
Synonyms: C13orf37; MOZART1; LOC440145; FLJ21869; MGC150539; RP11-11C5.2
Tractability: Small molecule: a structure with a bound ligand is known. PROTAC: ubiquitination databases record sites on it; its protein half-life has been measured.
Gene: Protein-coding gene on chromosome 13 (72,708,367 to 72,727,629, reverse strand). Ensembl gene ENSG00000204899.
Subcellular location: Cytoplasm, cytoskeleton, microtubule organizing center, centrosome; Cytoplasm, cytoskeleton, spindle
Pathways (Reactome):
Cell Cycle: Recruitment of NuMA to mitotic centrosomes; Recruitment of mitotic centrosome proteins and complexes
Gene Ontology:
Molecular function: protein binding
Biological process: gamma-tubulin complex localization; microtubule nucleation; microtubule nucleation by interphase microtubule organizing center; mitotic spindle assembly
Cellular component: centrosome; gamma-tubulin ring complex; spindle; cytosol; gamma-tubulin complex; interphase microtubule organizing center
Genetic constraint (gnomAD): Loss-of-function variants: 8 observed, 6.98 expected, observed/expected ratio (o/e) 1.15, 90% interval 0.66 to 1.83. That is too few expected variants to judge how well the gene tolerates losing a copy. Missense variants: 93 observed, 98.72 expected, observed/expected ratio (o/e) 0.94, 90% interval 0.8 to 1.12. Synonymous variants: 38 observed, 40.45 expected, observed/expected ratio (o/e) 0.94, 90% interval 0.72 to 1.23.
Homologues: Orthologues: chimpanzee MZT1 (100% identical), macaque MZT1 (100% identical), rabbit MZT1 (96% identical), pig MZT1 (93% identical), rat Mzt1 (89% identical), guinea pig MZT1 (88% identical), mouse Mzt1 (88% identical), dog MZT1 (76% identical), tropical clawed frog mzt1 (70% identical), zebrafish mzt1 (68% identical).
Diseases named in the same sentence as MZT1 in open-access papers:
MZT1 is named in the same sentence as 11 diseases in open-access papers, as found by Europe PMC text mining. Sharing a sentence is not in itself a finding about the gene and the disease. The quoted sentences say what the papers report.
cyst (1 paper, 2021). A sac-like closed membranous structure that may be empty or contain fluid or amorphous material. "We found that from the round spermatid stage onward the three t-γ-TuRC proteins begin to localize at the centriole adjunct, then also to the nuclear tip, and then finally to the surface of the mitochondria of the late elongating cyst, where they colocalize with γ-tubulin and Mzt1." (PMID 34660584, 2021).
MZT1 also shares sentences with these, for which no sentence is quoted: breast carcinoma (1 paper); cancer (1); colorectal adenocarcinoma (1); gastric carcinoma (1); lung carcinoma (1); ovarian carcinoma (1); prostate carcinoma (1); renal cell cancer (1); severe acute respiratory syndrome (1); viral infection (1).